HHIP (hedgehog interacting protein)
Description:
Modulates hedgehog signaling in several cell types including brain and lung through direct interaction with members of the hedgehog family.
Synonyms: HIP; FLJ20992
Tractability: Small molecule: a structure with a bound ligand is known; it has a high-quality binding pocket. Antibody: UniProt places it where antibodies can reach, with medium confidence; UniProt predicts a signal peptide or a membrane-spanning region; its Gene Ontology location is reachable by antibodies, with medium confidence. PROTAC: ubiquitination databases record sites on it.
Gene: Protein-coding gene on chromosome 4 (144,646,156 to 144,745,271, forward strand). Ensembl gene ENSG00000164161.
Subcellular location: Cell membrane; Secreted; Cytoplasm (Isoform 2)
Subcellular location (Human Protein Atlas): Nucleoplasm; Predicted to be secreted
Pathways (Reactome):
Signal Transduction: GLI proteins bind promoters of Hh responsive genes to promote transcription; Ligand-receptor interactions
Gene Ontology:
Molecular function: hedgehog family protein binding; protein binding; zinc ion binding
Biological process: negative regulation of signal transduction; negative regulation of smoothened signaling pathway; skeletal system morphogenesis
Cellular component: ciliary membrane; plasma membrane; cell surface; cytoplasm; extracellular region
Genetic constraint (gnomAD): Loss-of-function variants: 10 observed, 57.94 expected, observed/expected ratio (o/e) 0.17, 90% interval 0.1 to 0.29. The upper end of that interval is the gene's LOEUF score, 0.29, which puts it in group 1 of 6, group 1 being the genes least tolerant of losing a copy. Missense variants: 663 observed, 750.19 expected, observed/expected ratio (o/e) 0.88, 90% interval 0.83 to 0.94. Synonymous variants: 263 observed, 281.92 expected, observed/expected ratio (o/e) 0.93, 90% interval 0.84 to 1.03.
Homologues: Orthologues: chimpanzee HHIP (99% identical), macaque HHIP (99% identical), rabbit HHIP (98% identical), pig HHIP (97% identical), guinea pig HHIP (96% identical), mouse Hhip (94% identical), rat Hhip (94% identical), dog HHIP (83% identical), tropical clawed frog hhip (76% identical), zebrafish hhip (67% identical). Paralogues in human: HHIPL1 (28% identical), HHIPL2 (28% identical).
Diseases named in the same sentence as HHIP in open-access papers:
HHIP is named in the same sentence as 71 diseases in open-access papers, as found by Europe PMC text mining. Sharing a sentence is not in itself a finding about the gene and the disease. The quoted sentences say what the papers report.
lung carcinoma (15 papers, 2010 to 2023). "The decreased expression of HHIP in lung cancer tissues may be caused by various reasons, such as the methylation of CpG island in the promoter region of HHIP gene and the loss of heterozygosity (LOH)." (PMID 31765425, 2019). "Whether the GYPA association with COPD and lung cancer reflects an independent effect or linkage effect with the HHIP locus (LD≈0.70) is still debated." (PMID 21304900, 2011). "EDNRB and HHIP in this pathway were found to be downregulated in this study, which is consistent with previous reports regarding patients with lung cancer." (PMID 33046043, 2020). "The expression of HHIP in lung cancer cell lines significantly decreased compared with that in BEAS-2B cells." (PMID 31765425, 2019). "In lung cancer, however, the expression of HHIP cannot be induced because of epigenetic silencing, which leads to an aberrantly activated HH pathway." (PMID 27015549, 2016). "The HHIP protein is believed to be important in the bronchial epithelial response to smoking and epithelial repair processes in lung cancer." (PMID 21304900, 2011). "It belongs to the HHIP gene family and is expressed in the testis, thyroid gland, osteoarthritic cartilage as well as in pancreatic and lung cancers." (PMID 20187983, 2010). "In order to verify that whether the same result could be concluded in NSCLC cell lines in vitro, the expression of HHIP in four lung cancer cell lines (H1975, H358, H226, HCC827) and one normal lung cell line (BEAS-2B) were detected." (PMID 31765425, 2019). "Firstly, the HHIP expression in lung cancer was investigated." (PMID 31765425, 2019). "When the lung cancer cases were stratified by available spirometric data (n = 419 and n = 416 for HHIP and GYPA genotyping, respectively), into those with and without COPD (GOLD 2+ criteria), the distribution of the minor allele homozygote for both SNPs does not change significantly." (PMID 21304900, 2011). "The expression of the hedgehog-interacting protein (HHIP), a downstream target and a negative regulator of Hh signaling, was down-regulated in Cr(VI)-transformed BEAS-2B cells and primary lung cancers." (PMID 36497250, 2022). "The GG genotype of the HHIP (rs 1489759) SNP was found to be more prevalent in the control group compared to COPD (17% vs 11%, OR = 0.59, P = 0.006) and lung cancer (17% vs 13%, OR = 0.70, P = 0.05) groups." (PMID 21304900, 2011). "Based on the results of this study, the G0 genes conferring protection from COPD and lung cancer include the rs7671167 SNP (FAM13A gene on the Chr 4q22 locus) and the rs1489759 and rs2202507 SNPs (GYPA and HHIP genes on the Chr 4q31 locus)." (PMID 21304900, 2011). "Previous studies reported that HHIP overexpression could inhibit cell proliferation, migration, and invasion in HCC, gastric cancer, and lung cancer." (PMID 36482325, 2022). "Despite comparatively small sample sizes here, using this approach the authors have recently shown that the 15q25 (CHRNA 3/5) and 4q31 (HHIP/GYPA) loci might be relevant in both COPD and lung cancer." (PMID 21304900, 2011). "This is also relevant as the proportion of COPD patients who eventually develop lung cancer may be as high as 25–30% and the frequencies of several disease-related SNPs are very similar between lung cancer and COPD groups (eg FAM13A, HHIP)." (PMID 21304900, 2011). "This might explain why the lung cancer GWA studies to date failed to consistently identify the Chr4q31 (HHIP/GYPA) and Chr4q22 (FAM13A) loci as a protective loci, and the Chr 5q33 (ADAM19) locus as a possible susceptibility locus." (PMID 21304900, 2011).
gastric cancer (11 papers, 2013 to 2023). A primary or metastatic malignant neoplasm involving the stomach. "To clarify the potential mechanism caused low HHIP expression in gastric cancer cells, we next try to assess the de novo HHIP promoter methylation status." (PMID 33415068, 2020). "At present, the expression of the HHIP gene in human gastric cancer and its association with the CpG island methylation status of the promoter has not been reported." (PMID 25295121, 2014). "Consistently, we have already found that HHIP expression is downregulated in gastric cancer, however, it is still unknown of the underlying mechanism which causes low expression of HHIP in gastric cancer cells." (PMID 33415068, 2020). "However, the inhibitory role of HHIP as well as the underlying molecular mechanism of HHIP regulation in gastric cancer haven’t been fully elucidated yet." (PMID 33415068, 2020). "In conclusion, HHIP gene promoter CpG island methylation may be associated with the carcinogenesis of gastric cancer, so the detection of the HHIP gene methylation level may be a novel clinical marker for the early diagnosis of gastric cancer." (PMID 25295121, 2014). "Lower HHIP levels is positively associated with gastric cancer metastasis, which not only indicates HHIP could be served as a protective marker for gastric cancer, but also suggests restoring HHIP expression might be a potential therapeutic strategy for clinical treatment." (PMID 33415068, 2020). "Scholars have found that the expression of HHIP in gastric cancer tissues is reduced, and the overexpression of HHIP reduces the migration and invasion of GC." (PMID 34532291, 2021). "Further animal experiments are necessary to evaluate the effects of HHIP-overexpressing lentivirus used as a therapeutic agent for gastric cancer treatment." (PMID 33415068, 2020). "The results showed that HHIP expression was higher in adjacent normal gastric tissues than in gastric cancer tissues." (PMID 33415068, 2020). "Our results showed that HHIP overexpression significantly suppressed proliferation and migration of gastric cancer cells." (PMID 33415068, 2020). "Though the correlation between HHIP and gastric cancer malignance has been studied, the precise function of HHIP as well as the mechanism of HHIP regulation in gastric tumorigenesis remains to be uncertain." (PMID 33415068, 2020). "To assess the roles of HHIP in gastric cancer cell development, we first stably overexpressed HHIP in gastric cancer AGS cells by lentivirus-delivered HHIP (LV-HHIP) or empty control (LV-CON)." (PMID 33415068, 2020). "The constructed HHIP-overexpressing lentivirus demonstrated a high infection rate and produced high levels of HHIP in gastric cancer cells." (PMID 33415068, 2020). "Our results show that the constructed HHIP-overexpressing lentivirus is a promising therapeutic strategy to treat gastric cancer through downregulation of HH signaling pathway." (PMID 33415068, 2020). "Our study revealed a positive feed-back loop in regulation of HHIP expression in gastric cancer cells." (PMID 33415068, 2020). "We tested HHIP expression levels in all the specimens from 52 paired gastric cancer tissue and matched adjacent normal tissues by RT-PCR analysis." (PMID 33415068, 2020). "Overall, these results showed that lentiviral LV-HHIP had efficiently infected AGS cells and indeed increased the expression of HHIP in gastric cancer cells." (PMID 33415068, 2020). "Taken together, our study suggested that HHIP can modulate gastric cancer progression and metastasis via regulation of its de novo promoter methylation levels in a feedback manner." (PMID 33415068, 2020). "Consistently, our previous study has just demonstrated that HHIP had lower expression in gastric cancer cells compare to the normal control cells." (PMID 33415068, 2020). "To this aim, we have investigated the biological function as well as the potential mechanism of HHIP regulation in gastric cancer in this study." (PMID 33415068, 2020).
gastric cancer (continued). "Human hedgehog-interacting protein (HHIP), a negative regulator of hedgehog (HH) signaling pathway, has been reported to be dysregulated in many types of cancer, including gastric cancer." (PMID 33415068, 2020). "Meanwhile, other studies have shown that inhibiting the methylation of HHIP promoter can inhibit the proliferation and migration of human gastric cancer cells." (PMID 31765425, 2019). "Based on the RT-PCR results, HHIP mRNA was found to be expressed in the human gastric cancer tissues and adjacent gastric tissues, and was found to have almost no expression in the AGS cells." (PMID 25295121, 2014). "The positive rate of HHIP mRNA expression in the gastric cancer tissues was 30% (18/60) compared with 66.67% in the adjacent normal tissues (40/60)." (PMID 25295121, 2014). "The degree of methylation of the HHIP gene promotor in the peritumoral tissues (17.7±3.59%) was significantly lower than that in the gastric cancer tissues (62.9±6.14%) and in the AGS cells (99.7±0.67%) (P<0.05)." (PMID 25295121, 2014). "The expression of the HHIP gene, a negative regulator of Hh signaling, has been shown to be reduced in gastric cancer tissues, but retained in normal gastric tissues or atypical hyperplasia." (PMID 25295121, 2014). "The level of HHIP methylation increased significantly in normal gastric mucosa, gastric cancer and gastric cancer cell lines." (PMID 25295121, 2014). "The study found that the level of HHIP gene promoter methylation in peritumoral tissues (17.7±3.59%) was significantly lower than that in gastric cancer tissues (62.9±6.14%) and AGS cells (99.7±0.67%) (P<0.05)." (PMID 25295121, 2014). "It was found that the expression level of the HHIP mRNA in the gastric carcinoma tissues was significantly lower than that in the adjacent tissues (0.82±0.38 vs. 1.60±0.26, respectively; P<0.001)." (PMID 25295121, 2014). "The present study aimed to analyze the methylation of the HHIP gene in patients with gastric carcinoma." (PMID 25295121, 2014). "The HHIP mRNA expression in 60 human gastric carcinnoma tissues, peritumoral tissues and the gastric carcinoma AGS cell line were detected by reverse transcription polymerase chain reaction (RT-PCR)." (PMID 25295121, 2014). "Hedgehog signaling is frequently activated in esophageal cancer, gastric cancer, and pancreatic cancer due to transcriptional upregulation of Hedgehog ligands and epigenetic silencing of HHIP1/HHIP gene, encoding the Hedgehog inhibitor." (PMID 24066008, 2013). "We speculate that HHIP overexpression inhibits human gastric cancer growth and metastasis via decrease of CpG island methylation levels on its own promoter." (PMID 33415068, 2020). "In summary, we have established a lentiviral vector to overexpress the HHIP gene in gastric cancer cells and found that overexpression of HHIP remarkably inhibited the proliferation and invasion of AGS cells, accompanied by decreased de novo HHIP promoter methylation levels in AGS cells." (PMID 33415068, 2020). "Since HHIP is a negative regulator of HH signaling, the upregulation of HHIP may play a critical role in suppressing HH signaling pathway in gastric cancer." (PMID 33415068, 2020). "HHIP overexpression might be used to inhibit human gastric cancer growth and metastasis via reducing CpG island methylation on its own promoter." (PMID 33415068, 2020). "It has been reported that HHIP was downregulated in gastric cancer, which suggests HHIP might function as a tumor suppressor in the gastric tumorigenesis." (PMID 33415068, 2020). "Our results suggested that higher HHIP levels showed higher metastasis free rate, which not only hints the protective role of HHIP in gastric cancer development, but also provides evidence to serve HHIP as a potential biological target for gastric cancer treatment." (PMID 33415068, 2020). "Therefore, our data showed that HHIP overexpression suppressed the progression of gastric cancer by inhibiting cell proliferation, migration, and invasion." (PMID 33415068, 2020).
gastric cancer (continued). "Importantly, we also found that HHIP positive specimens showed higher metastasis free rate of gastric cancer." (PMID 33415068, 2020). "All suggests that HHIP might be an efficient target and overexpression of HHIP by a lentiviral vector might be a promising therapeutic strategy for gastric cancer treatment." (PMID 33415068, 2020). "GATA3 was demonstrated to interact with HIF-1α to enhance cancer cell invasiveness, and inhibition of HHIP promoter methylation suppressed human gastric cancer cell proliferation and migration, which would affect the treatment and prognosis of patients with gastric cancer." (PMID 31281358, 2019). "There is currently a lack of studies with regard to HHIP gene defects and mutations in gastric cancer." (PMID 25295121, 2014). "This study analyzed the occurrence of HHIP gene CpG island methylation in gastric cancer." (PMID 25295121, 2014). "HHIP and the specific mechanism of gastric cancer require further study." (PMID 25295121, 2014). "Previous research has demonstrated that HHIP acts as a tumor suppressor in a variety of malignancies, such as liver cancer, glioblastoma, and gastric cancer, According to bioinformatic analysis, miR‐630 may bind to HHIP, which was verified by dual‐luciferase reporter assay." (PMID 37039160, 2023). "Hence increasing HHIP expression by exogenous vectors might be a promising therapeutic strategy for gastric cancer." (PMID 37568084, 2023). "Interestingly, our results suggest that there might be a positive feed-back regulating HHIP expression by modulating its own promoter methylation levels in gastric cancer cells." (PMID 33415068, 2020). "Thus, HHIP might be used as a biological target for gastric cancer, which definitely needs more clinical research in future." (PMID 33415068, 2020). "Thus, all these data suggested that overexpression of HHIP could inhibits HHIP promoter methylation in human gastric cancer cells in a feedback manner." (PMID 33415068, 2020). "Moreover, we also identify an interesting feedback loop functions as a critical event to finely regulate HHIP expression: HHIP overexpression can decrease the CpG island methylation status on its de novo promoter, which further inhibits gastric cancer progression and metastasis." (PMID 33415068, 2020). "HHIP may be used as an inhibitor of cell metastasis and a prognostic biomarker in gastric cancer." (PMID 31765425, 2019). "Therefore, HHIP gene CpG island hypermethylation may decrease the expression of HHIP, which maybe participate in the carcinogenesis of gastric cancer, therefore methylation in HHIP gene CpG islands may be a good detection index for gastric cancer." (PMID 25295121, 2014). "However, the potential molecular mechanism of HH signaling, especially the dysregulation of Human hedgehog-interacting protein (HHIP) gene, is largely uncertain in gastric cancer." (PMID 33415068, 2020). "Treating gastric cancer AGC cell line with 5aza-dC effectively reduced cell viability and induced apoptosis, suggesting a role of canonical Hh pathway activation in gastric tumorigenesis through hypermethylation and subsequent downregulation of the PTCH1 and HHIP negative regulators." (PMID 34572373, 2021). "In this study, we observed that overexpression of HHIP significantly inhibited the proliferation and invasion of AGS cells, which might provide evidences to further support the tumor suppressor function of HHIP in gastric cancers." (PMID 33415068, 2020). "Furthermore, HHIP expression was higher in adjacent non-cancerous tissue compared to matched gastric cancer tissue." (PMID 33415068, 2020).
chronic obstructive pulmonary disease (10 papers, 2015 to 2025). A chronic and progressive lung disorder characterized by the loss of elasticity of the bronchial tree and the air sacs, destruction of the air sacs wall, thickening of the bronchial wall, and mucous accumulation in the bronchial tree. "The HHIP gene, encoding Hedgehog interacting protein, has been implicated in chronic obstructive pulmonary disease (COPD) by genome-wide association studies (GWAS), and our subsequent studies identified a functional upstream genetic variant that decreased HHIP transcription." (PMID 25763110, 2015). "Variants within regulatory sequences of HHIP expression are associated with chronic obstructive pulmonary disease (COPD)." (PMID 41000054, 2025). "Genetic variants annotated to the hedgehog interacting protein (HHIP) are robustly associated with chronic obstructive pulmonary disease (COPD)." (PMID 28566717, 2017). "Our example applications highlight the potential significance of BSG receptor in SARS-CoV-2 infection as well as the involvement of HHIP and TGFB2 in the development and progression of chronic obstructive pulmonary disease." (PMID 38617561, 2024). "One plausible explanation for the pleiotropic effects of this region is that it hosts the Hedgehog (Hh)-interacting protein (HHIP) gene, which is associated with multiple pulmonery traits, such as FEV1/FVC ratio, chronic obstructive pulmonary disease (COPD) and lung cancer." (PMID 38040712, 2023). "HHIP and CHI3L1 were both over-expressed in CF as well as in chronic obstructive pulmonary disease (COPD) and asthma." (PMID 32492951, 2020). "Highly significant DEGs including CYP1A1, HHIP (hedgehog interacting protein), MUC5AC, and CYP2A6 might be related to the pathophysiology of chronic obstructive pulmonary disease." (PMID 38137330, 2023).